KRTAP4-7 (keratin associated protein 4-7)
Description:
In the hair cortex, hair keratin intermediate filaments are embedded in an interfilamentous matrix, consisting of hair keratin-associated proteins (KRTAP), which are essential for the formation of a rigid and resistant hair shaft through their extensive disulfide bond cross-linking with abundant cysteine residues of hair keratins. The matrix proteins include the high-sulfur and high-glycine-tyrosine keratins.
Synonyms: KAP4.7; KRTAP4.7
Tractability: No criterion of Open Targets' tractability assessment is met for any kind of drug.
Gene: Protein-coding gene on chromosome 17 (41,084,150 to 41,085,144, forward strand). Ensembl gene ENSG00000240871.
Pathways (Reactome):
Developmental Biology: Keratinization
Gene Ontology:
Molecular function: protein binding
Biological process: hair cycle
Cellular component: cytosol; keratin filament
Genetic constraint (gnomAD): Loss-of-function variants: 1 observed, 2.38 expected, observed/expected ratio (o/e) 0.42, 90% interval 0.14 to 1.65. That is too few expected variants to judge how well the gene tolerates losing a copy. Missense variants: 199 observed, 175.61 expected, observed/expected ratio (o/e) 1.13, 90% interval 1.01 to 1.27. Synonymous variants: 70 observed, 56.85 expected, observed/expected ratio (o/e) 1.23, 90% interval 1.01 to 1.5.
Homologues: Orthologues: mouse Krtap4-7 (70% identical), mouse Krtap4-24 (67% identical), rat Krtap9-7 (54% identical). Paralogues in human: KRTAP4-9 (94% identical), KRTAP4-11 (88% identical), KRTAP4-12 (88% identical), KRTAP4-6 (88% identical), KRTAP4-8 (81% identical), KRTAP4-5 (80% identical), KRTAP4-3 (71% identical), KRTAP4-2 (68% identical), KRTAP4-4 (66% identical), KRTAP4-1 (58% identical), KRTAP10-7 (51% identical), KRTAP9-2 (50% identical), and 35 more.